CD4 (CD4 molecule)
Diseases named in the same sentence as CD4 in open-access papers (continued):
Sharing a sentence is not in itself a finding about the gene and the disease.
oral candidiasis (64 papers, 2006 to 2025). Infection of the mucosal lining of the mouth with the fungus Candida albicans. "Antiretroviral therapy can reduce the risk of developing oral candidiasis through the enhancement of the immune system, secondary to the elevation of CD4 count." (PMID 38373939, 2024). "Oral candidiasis was found to be the most prevalent infectious dermatoses, associated with a mean CD4 count of 97 cells/mm3." (PMID 37581910, 2023). "Oral candidiasis was the most prevalent of infectious dermatoses and was associated with a mean CD4 count of 97 cells/mm3." (PMID 37581910, 2023). "Independent studies carried out in India in 2011 and in France in 2014; showed an association between oral candidiasis and CD4 <200 cells/mm3 with OR= 6 and OR=3 respectively." (PMID 37545607, 2023). "The occurrence of oral candidiasis was more likely to be associated with the drop in CD4+ T-cell counts." (PMID 36232165, 2022). "Oral candidiasis was furthermore associated with high fungal burdens of Candida albicans and a CD4+ T-cell number <200/μl." (PMID 35250957, 2022). "This is similar to reports from Tanzania, Ghana, Cameroon, and India, where oral candidiasis is associated with CD4+ T-cell counts <200 cells/μl." (PMID 35250957, 2022). "This is consistent with other findings which indicated that stage III is characterized by severe weight loss, chronic diarrhea, fever, oral candidiasis, and CD4+ cell count <200 cells/mm3." (PMID 36415339, 2022). "In our study, oral candidiasis emerged irrespectively of HAART when CD4+ T-cell counts were <200 cells/μl and was mainly caused by C. albicans." (PMID 35250957, 2022). "This was a statistically significant association between the prevalence of oral candidiasis and low CD4 cells (P<0.001)." (PMID 32774600, 2020). "Oral candidiasis was observe more frequently among individuals with CD4 cell less than 200cells/μl (13.23%) However, the association between CD4 cell and the prevalence of oral candidiasis was statistically significant (P<0.001)." (PMID 32774600, 2020). "Among all studied mucocutaneous lesions, only oral candidiasis (P=0.002) and furuncle (P=0.006) were significantly associated with low CD4 cell counts." (PMID 32850174, 2020). "The low absolute CD4+ T-lymphocyte count has traditionally been cited as the greatest risk factor for the development of oral candidiasis and current guidelines suggest increased risk once CD4+ T lymphocyte counts fall below 200 cells/μl." (PMID 32774600, 2020). "The present research also found oral candidiasis to be a mucocutaneous disorder with significant association with low CD4 counts, which is consistent with previous studies." (PMID 32850174, 2020). "Oral candidiasis was the only lesion found to have a significant association with CD4+ count of less than 350 cells/mm3, (OR = 2.691, p < 0.001, CI = 1.608–4.502)." (PMID 25432363, 2014). "There was significant association between oral candidiasis and immunosuppression measured as CD4+ less than 350 cells/mm3 (OR = 2.69, CI = 1.608-4.502, p < 0.001)." (PMID 25432363, 2014). "Among HIV-positive patients, conjunctival pallor, MUAC <20 cm, dyspnea, oral hairy leukoplakia (OHL), oral candidiasis, and gingivitis were significantly associated with <350 CD4 cells/mm3." (PMID 24560255, 2014). "At bivariate analysis, CD4+ count of less than 350 cells/mm3, was found to be significantly associated with presence of oral candidiasis (OR = 2.691, p < 0.001,CI = 1.608-4.502)." (PMID 25432363, 2014). "We have previously shown that hospitalization and receipt of antibiotics were risk factors for oropharyngeal colonization by Candida and that a low CD4+ lymphocyte count (≤ 200 cells/mm3) was a risk factor for developing oral candidiasis." (PMID 16423306, 2006). "We hypothesize that lower CD4+ T cell counts, smoking status, rural residence, and periodontal disease are significantly associated with the presence of oral candidiasis in this population." (PMID 40428813, 2025).
oral candidiasis (continued). "Therefore, it is likely that oral candidiasis will develop in cases of vitamin D deficiency, even with CD4 > 200 cells/mm3." (PMID 38373939, 2024). "Several authors reported the association of oral candidiasis with low CD4 cell counts." (PMID 37581910, 2023). "Oral candidiasis and furuncle were significantly associated with decrease in CD4 cell counts." (PMID 32850174, 2020). "Low CD4 count has been seen as a major risk factors for oral candidiasis." (PMID 32774600, 2020). "In PLWH, risk factors for PCPinclude a CD4 T lymphocyte count of less than 200 cells/mm3, a history of PCP, a history of oral candidiasis, and a high plasma HIV RNA level." (PMID 40260188, 2025). "Expansion of PMN-MDSCs in response to oral candidiasis was confirmed by the immunosuppressive activity on CD4 + T cells by Ly6G + Arg1 + cells." (PMID 37886517, 2023). "Oral candidiasis was assessed, while viral load (VL) and CD4-count were measured on Abbott m2000rt and Cy-flow counter platforms, respectively." (PMID 37545607, 2023). "The occurrence of opportunistic infections such as oral candidiasis is found in PLHIV with a CD4 count <200 cells/mm3." (PMID 37545607, 2023). "A statistically significant correlation was found between a CD4 count <200 cells/mm3 and the frequency of oral candidiasis (P<.001)." (PMID 37581910, 2023). "For treatment-naive patients with a viral load ≥1000 copies/ml and severe immune depression (CD4 <200 cells/mm3) should be managed and monitored for oral candidiasis." (PMID 37545607, 2023). "Children undergoing ART with a duration longer than 3 years had a significantly lower prevalence of oral candidiasis and CD4+ T-cell counts." (PMID 36231240, 2022). "There was also a statistically significant relationship between oral candidiasis and a CD4 count of less than 100 cells/ mm3 (p=0.008)." (PMID 35867921, 2022). "In the infectious category, the most common cutaneous infection was caused by herpes simplex virus (HSV) (52.4%; mean of CD4 count: 405 cell/mm3), followed by oral candidiasis (47.6%; mean of CD4 count: 375 cell/mm3)." (PMID 32850174, 2020). "The distribution of the prevalence of oral candidiasis at different CD4 cell levels, oral candidiasis (13.23%) was more frequent in individuals with <200 cells/μl and was a common observation with other studies." (PMID 32774600, 2020). "Distribution of the prevalence of oral candidiasis according to sex, age and CD4 levels: the frequency of oral candidiasis was more among females (30.69%) than in males (12.17%) in this study." (PMID 32774600, 2020). "Approximately 50% newly HIV diagnosed patients with low CD4 T-cell count commonly show oral candidiasis as an initial presentation of symptomatic HIV-infected patients." (PMID 31771096, 2019). "This burden was estimated by assuming that 90% of untreated HIV patients with CD4 counts <200 × 106/mL developed oral candidiasis." (PMID 29937480, 2018). "We describe here a 30-year-old African American female who presented with fever, generalized rash, cervical lymphadenopathy, and oral candidiasis and was found to have Kikuchi-Fujimoto disease on lymph node biopsy with low CD4 count." (PMID 25313340, 2014). "The other four patients had oral candidiasis and their CD4 counts were 14/μL, 84/μL, 229/μL, and 367/μL, respectively." (PMID 18416821, 2008). "Several presenting features were statistically associated with the diagnosis of CM, including confusion, social withdrawal, seizures, fever, tachycardia, meningismus, oral candidiasis, and low Glasgow coma scales and CD4 count." (PMID 17493266, 2007). "However, they noted a significantcorrelation only between an increase in CD4+ T-cell count and a decrease in oral candidiasis, which provides an interesting perspectiveon our own findings." (PMID 40162460, 2024).
oral candidiasis (continued). "Distribution of oral candidiasis according to CD4 count: based on CD4 cell count, all oral candidiasis cases observed among naïve patients had CD4<200 cells/mm3, with 30.4% (7/23) and 17.4% (4/23) having the erythematous and pseudomembranous forms, respectively." (PMID 37545607, 2023). "We noticed that the “AKT signaling” (R-HSA-1257604) pathway is enriched in the DNMT1 core module, and it is worthwhile to mention that AKT signaling is crucial for T-cell differentiation and it encourages naive CD4 T cells to differentiate into Th17 to prevent oral candidiasis." (PMID 37900175, 2023). "Apart from this CD4 value, oral candidiasis was also found in different forms in PLHIV." (PMID 37545607, 2023). "Additionally, the relationship between oral candidiasis and CD4 less than 100 cells/mm3 indicates the potential role of oral candidiasis as an essential marker of weakened immune status in HIV patients." (PMID 35867921, 2022). "However, the duration of ART was also positively associated with CD4+ T-cell counts, as those children taking ART for three years or more were less likely to have oral candidiasis and CD4+ T-cell counts less than 250 CD4+ T cells/mm3." (PMID 36231240, 2022). "Statistical analysis showed that CD4+ count plays a crucial role in oral candidiasis." (PMID 25745611, 2015). "Therefore, oral candidiasis can be used as an index for immunosuppression depicted by CD4+ less than 350 cells in this study population." (PMID 25432363, 2014). "In multivariate regression analysis, male gender, age>32 years, conjunctival pallor, shortness of breath, OHL, oral candidiasis, and MUAC <20 cm were independently associated with CD4 cell counts <350 cells/mm3.CD4 cell counts <50 cells/mm3 were associated with OHL and MUAC <20 cm." (PMID 24560255, 2014). "The prevalence of oral candidiasis in this study was 29.3% with the median CD4 counts 45.3cells/ul, which indicated that the occurrence of oral candidiasis helped physicians in resource constrained regions in China to diagnose the clinical progression of HIV infection." (PMID 24204583, 2013). "Untreated HIV patients (ART eligible but not yet on ART) and oral candidiasis were associated with bacteremia in bivariate models but were not retained in the multivariate model after adjustment for CD4 count." (PMID 24386229, 2013). "Major studies from India reports chronic diarrhoea, gastrointestinal infection as the most common OIs associated with HIV patients but our study revealed it to be the second major complication following oral candidiasis whose median CD4+ count was estimated to be around 167 cells/mm3." (PMID 21396133, 2011). "Oral candidiasis group presented with mean CD4+ count of 212.61/mm3." (PMID 20418994, 2010). "Oral candidiasis may be considered as a clinical surrogate for severe CD4+ depletion." (PMID 21396133, 2011). "Here, we performed the first study in Chad on the prevalence of oral yeasts carriage and oral candidiasis in HIV-positive subjects from southern Chad and analyzed the influence of HAART, CD4+ T-cell numbers, and antimycotics in 589 patients." (PMID 35250957, 2022). "This is in agreement with clinical findings that plasma HIV-RNA levels, regardless of CD4 count, was the only correlate of oral Candida colonization, and oral candidiasis usually resolved after initiation of HAART, even though the CD4 count remained low." (PMID 28748029, 2017). "The occurrence of oral candidiasis is recognized as an indicator of immune suppression and is often found in HIV infected patients with CD4 counts fewer than 200 cells/μL." (PMID 27413381, 2016). "Sexual behavior, CD4+ count, HIV-RNA viral load (VL), history of HAART, GI symptoms, GI diseases, and oral candidiasis were assessed." (PMID 23555571, 2013). "The occurrence of oral candidiasis was recognized as an indicator of immune suppression, and those were often found in HIV-infected patients with CD4 counts fewer than 200cells/ul." (PMID 24204583, 2013).
oral candidiasis (continued). "The cART was found to better enhance CD4 cell counts and diminish the viral loads than monotherapy and dual therapy, as the children receiving the latter had a similar prevalence of oral candidiasis to those without therapy." (PMID 36231240, 2022). "Oral candidiasis is one of the first few signs indicating immunosuppression or a failure of ART, which coincides with the findings that fewer children undergoing cART had less than 250 CD4+ T cells/mm3." (PMID 36231240, 2022). "Oral candidiasis is estimated in 71 patients with CD4 counts <200/μL, but we have not been able to estimate the incidence of oral candidiasis in non-HIV patients, likely to be much higher." (PMID 33233367, 2020). "Although 90% of patients had CD4+ lymphocyte counts below 200 cells/mm3, studies have not shown any correlation between oral candidiasis and low CD4+ lymphocyte counts, but they have shown correlation with a high viral load." (PMID 28303122, 2017). "Of all CE patients, 56.5% (35/62) had no GI symptoms, 30.6% (19/62) had CD4 +≥200 cells/μL, and 55.3% (21/38) had no oral candidiasis." (PMID 23555571, 2013). "Endoscopy is useful as it can detect CE, even severe CE, in patients without GI symptoms, those with high CD4 counts, and those without oral candidiasis." (PMID 23555571, 2013). "Of them, 56.5% (35/62) had no GI symptoms, 30.6% (19/62) had CD4 + ≥200 cells/μL, and 55.3% (21/38) had no oral candidiasis." (PMID 23555571, 2013). "In this study, we performed endoscopy for a large number of HIV-infected patients including those with no GI symptoms, high CD4 counts, or no oral candidiasis." (PMID 23555571, 2013). "Another study demonstrated that the following factors made HIV-infected individuals more susceptible to oral candidiasis: low CD4 count, high viral load, drug composition or nonuse of HAART, oral carriage of Candida spp., and a history of oral candidiasis, which is consistent with our findings." (PMID 38373939, 2024). "Endoscopy is a valuable definitive diagnostic method for CE but may not be indicated for asymptomatic patients or for those with high CD4 counts or without oral candidiasis." (PMID 23555571, 2013). "However, under these conditions, endoscopy may not be indicated for asymptomatic patients, or for those with high CD4 cell counts or without oral candidiasis." (PMID 23555571, 2013). "In a resource-poor setting without access to CD4+ T-cell counting and HIV viral load measurements, oral candidiasis is one of the most important clinical markers of HIV infection, disease progression, CD4+ T-cell status, and can even give a hint to antiretroviral therapy failure." (PMID 35250957, 2022). "López-Dupla and colleagues compared several factors between patients with oral candidiasis and those with CE in the pre-HAART era and found that the CD4:CD8 ratio was significantly lower in CE patients and that lymphocyte and CD4+ cell counts were lower, albeit non-significantly, in CE patients." (PMID 23555571, 2013).
visceral leishmaniasis (64 papers, 2003 to 2025). A severe form of leishmaniasis characterized by irregular bouts of fever, substantial weight loss, swelling of the spleen and liver, and anemia (which may be serious). "In diseases caused by intracellular parasites, such as visceral leishmaniasis (VL), various immune modulators have the capacity to negatively impact protective CD4+ T cell functions." (PMID 29075269, 2017). "In humans, polymorphism for CXCR2 as well as for Notch 3 Delta-like 1 ligand, which drives CD4 T helper 1 cell responses, contributes to susceptibility to visceral leishmaniasis and affects the outcome of the disease." (PMID 25874567, 2015). "Recently, regulatory T (Treg) cells have been implicated in IL-10 production and CD4+ suppression in visceral leishmaniasis." (PMID 25268355, 2014). "Thus, Leishmania-infected and ART-naïve PWH with low CD4+ T cells (<200 cell/μL) and high viral load are at high risk of developing severe visceral leishmaniasis." (PMID 37601355, 2023). "HIV infection leads to worse treatment outcomes in visceral leishmaniasis (VL) and increases the risk of post-treatment relapse, suggesting that similar effects may be observed in other low CD4+ T cell states." (PMID 28493863, 2017). "Lastly, miltefosin, a phosphorylcholine esther of hexadecanol is a medicine used for the treatment of visceral leishmaniasis in HIV-1 co-infected individuals which has been shown to reduce HIV-1 replication in CD4+ T-cells that was, in part, caused by the onset of IFN type I production by DCs." (PMID 26808476, 2016). "IL-10 is a critical regulatory cytokine involved in the pathogenesis of visceral leishmaniasis caused by Leishmania donovani and clinical and experimental data indicate that disease progression is associated with expanded numbers of CD4+ IFNγ+ T cells committed to IL-10 production." (PMID 22911108, 2012). "Visceral leishmaniasis (VL) is a severe human vector-borne CD4-immunosuppressive disease that can be lethal if untreated soon after symptoms arise." (PMID 40666521, 2025). "This contrasts with patients affected by so-called Old and New World visceral leishmaniasis, who, despite profound suppression of the CD4+/Th1-type immune response, often exhibit a significant shift toward DTH, assessed by MST reactivity following treatment." (PMID 40764931, 2025). "Parasite antigens and plasma lipopolysaccharide (LPS) levels from luminal origin in visceral leishmaniasis (VL) patients are correlated with cellular activation and low CD4+T cell counts." (PMID 40929455, 2025). "A substantial body of literature has established the protective role of CD4+ T cells in experimental cutaneous and visceral leishmaniasis models." (PMID 39702382, 2024). "Impaired control of parasites can in part be explained by hampered CD4+ T cells effector functions in visceral leishmaniasis (VL) patients." (PMID 38408097, 2024). "In visceral leishmaniasis (VL), antigen specific CD4+ T cell responses are muted hindering the control of the Leishmania donovani infection." (PMID 38408097, 2024). "CD4+ T cells with this Type 1 regulatory cell phenotype have been observed in experimental visceral leishmaniasis." (PMID 38335163, 2024). "Patients coinfected with HIV and visceral leishmaniasis exhibited lower splenic CD4+ cell density and reduced expression of genes such as IL15." (PMID 38843306, 2024). "In this review, we will discuss recent findings about two of these molecules; the NK cell granule protein Nkg7 and the anti-inflammatory cytokine TGFβ, and describe how they impact CD4+ T cell functions and immune responses during visceral leishmaniasis." (PMID 38881737, 2024). "We have recently identified the transcription factor IFN regulatory factor 5 (IRF-5) as a detrimental player in the survival of CD4+ T cells during chronic visceral leishmaniasis." (PMID 37227774, 2023).